OAS2 (2'-5'-oligoadenylate synthetase 2)
Diseases named in the same sentence as OAS2 in open-access papers (continued):
Sharing a sentence is not in itself a finding about the gene and the disease.
COVID-19 (44 papers, 2020 to 2026). A disease caused by infection with severe acute respiratory syndrome coronavirus 2. "These analyses showed differences only in proportions of the rs1293767 (OAS2) variant between asymptomatic and severe COVID-19." (PMID 38673053, 2024). "Our findings indicate that individuals possessing the C/G genotype of the OAS2 gene variant rs1293767 have 60% lower odds (or a reduction in risk by 60%) of experiencing severe COVID-19 symptoms." (PMID 38673053, 2024). "OAS2 is an interferon stimulated gene involved in interferon response, it was previously reported to be associated with COVID-19 severity." (PMID 36389738, 2022). "The COVID-19-risk variants in the OAS1/OAS3/OAS2 locus were also associated with reduced expression of OAS3 in certain T cell subsets but not in monocytes, NK cells, or B cells." (PMID 34799557, 2021). "Similarly, in a previous study in the Mexican population, the genetic variant OAS2 rs1293767 was associated with COVID-19 infection and severe disease in the general population and in patients with COVID-19." (PMID 38673053, 2024). "Furthermore, individuals with the C allele of the same gene variant (rs1293767 in OAS2) exhibit a 70% decrease in the likelihood of developing any COVID-19 symptoms." (PMID 38673053, 2024). "In this study, we examined the frequency of three gene variants within the OAS family (OAS1, OAS2, and OAS3) and one in RNASEL, in relation to the manifestation of COVID-19 symptoms and the overall disease prognosis." (PMID 38673053, 2024). "The C allele and the C/G genotype of the rs1293767 OAS2 genetic variant and the T allele and the C/T genotype of the rs2285932 genetic variant of OAS3 had lower odds of developing COVID-19 symptoms among the studied Mexican population." (PMID 38673053, 2024). "In this study, we analyzed the frequency of three gene variants of OAS (OAS1, OAS2, and OAS3) and one in RNASEL, and evaluated their association with the occurrence of COVID-19 symptoms and disease outcome." (PMID 38673053, 2024). "The variant rs10735079 lies in the interferon-inducible OAS gene cluster (OAS1, OAS2, and OAS3) and was associated with critical COVID-19 illness (P = 1.65 × 10−8) in genome-wide significant associations." (PMID 37745867, 2023). "The ‘dark’ genes JAK1 and OAS2 encoded the proteins JAK and 2’-5’OAS (2’-5’-Oligoadenylate synthetase) in the JAK-STAT signaling pathway in the Coronavirus disease—COVID-19, respectively." (PMID 37853311, 2023). "Nonetheless, the current literature is conflicting regarding the OAS2 role in the pathophysiology of COVID-19." (PMID 36389738, 2022). "A recent study found that OAS2 belongs to a subset of interferon-stimulated genes, and OAS2 can be regarded as a potential candidate for a drug target in COVID-19 therapy." (PMID 35812523, 2022). "Meanwhile, OAS2 was reported to be highly expressed in positive COVID-19 patients and acts as a candidate drug target for COVID-19 treatment." (PMID 34603483, 2021). "Both previously published RNA sequencing analysis of the same samples, and RT-qPCR experiments done for this project confirm that transcriptional products of IFI27 and OAS2 are upregulated in COVID-19 samples in comparison with non-COVID-19 control patients." (PMID 34034806, 2021). "Another study found increased levels of IFI27 and OAS2 in COVID-19 patients." (PMID 37053191, 2023). "This pointed to a robust anti-viral response only in COVID-19 patients at D1 which was substantially muted by D7, as represented by the temporal expression patterns of key antiviral and interferon-related genes such as OAS2 and IFIT1." (PMID 37090709, 2023). "Some studies suggest that OAS gene family may provide a potential therapeutic target for COVID-19 if the gene is mutated on chromosome 12q24.13 (a gene cluster that encodes OAS1, OAS2, and OAS3 antiviral restriction enzyme activators)." (PMID 36162993, 2022).
COVID-19 (continued). "Notably, OAS2 was recently suggested as one of the hub genes for coordinating innate immune responses in COVID-19 and a potential to-be-augmented target for the treatments of this illness." (PMID 35386719, 2022). "OAS1, OAS2, and OAS3 were overexpressed in hospitalized patients with severe COVID-19 compared with healthy subjects (HS) (log2 fold change [95% CI]: OAS2: 4.312 [4.161-4.602], OAS3: 1.660 [1.485-1.916]; p = 0.0040 for both)." (PMID 41899113, 2026). "Another study highlighted that a Neanderthal-derived haplotype encompassing the genes OAS1, OAS2, and OAS3 conferred protection against COVID-19, with OAS3 showing the most substantial correlations." (PMID 38673053, 2024). "Several IFN-related genes, such as SPATS2L, OAS2, ISG15, ZBP1, and IFI44L, exhibited similar patterns of upregulation across both dengue and COVID-19 datasets, while others, such as AIM2 and RTP4, showed distinct regulation." (PMID 38444851, 2024). "The increased expression of selected IFN-I (OAS1, OAS2, and IFIT1) and inflammasome related genes (CASP1, CASP5, NLRC5 and NAIP) between COVID-19 and HC PMNs was confirmed by RT-qPCR." (PMID 39172744, 2024). "Through COVID-19-relevant transcriptome and enrichment gene sets, seven druggable targets with COVID-19-relevant functions were identified, including CCR9, CXCR6, XCR1, IL10RB, OAS1, OAS2, and OAS3." (PMID 37886583, 2023). "Results demonstrated that OAS1, OAS2, OAS3, and OASL were all highly expressed in SARS-CoV-2 infected NHBE (OAS 1 − 3, P < 0.01) and in the blood leucocytes of COVID-19 patients (all P < 0.001)." (PMID 36949448, 2023). "Asthma and COVID-19 share two genome-wide significant genes, including ABO at the 9q34.2 region and OAS2 at the 12q24.13 region." (PMID 35386719, 2022). "The optimal 24 feature genes, which were further analyzed by consulting the retrieved literature, we found that four genes (XAF1, OAS2, CES1, RPS8) have been reported in COVID-19." (PMID 35812523, 2022). "We identified accessible proxy SNPs in LD with the COVID-19 sentinel rs10774671 in the promoter of OAS3, and accessible proxies interacting with OAS1 and OAS2 in all immune cell types analyzed." (PMID 35659055, 2022). "Seven of our significant genes higher (GALNT14, OAS1, CCRL2, OAS3, CCR1, OAS2, SIPA1L2) in COVID-19 and two lower (HLA-DPB1, HLA-DQA2) were identified to overlap." (PMID 34335605, 2021). "Comparison of severe and mild Symptomatic COVID-19 cases revealed an upregulation of CD177, the neutrophil marker, CXCL16, MAPKMAPK2 and IRF2BP2 with downregulation of ISGs; IFIT, IFIT3, OAS1, OAS2, LY6E and MX1 in severe cases." (PMID 34824360, 2021). "OAS1, OAS2, OAS3, IFIT1, IFIT3, IFI44, IFI44L and IFITM1: Current COVID-19 genetic studies incline to analyze those genes together." (PMID 34109284, 2021). "Several other loci show no previously documented genome-wide significant associations, despite the high significance and attractive candidate genes for COVID-19 (for example, CXCR6, LZTFL1, IFNAR2 and OAS1/OAS2/OAS3 loci)." (PMID 34237774, 2021). "Although both subtypes are significantly up-regulated in the plasma of COVID-19 patients, only IFNA2 levels correlate with the IFN-α scores and with mRNA expression of well recognized IFN-inducible genes (ISGs), such as ISG15 and OAS2." (PMID 35217532, 2022). "Finally, in individuals with moderate SARS-CoV-2 infection, 2’-5’-Oligoadenylate Synthetase 1 (OAS1), OAS2, OAS3, and T cell Immunoreceptor with Ig and ITIM domains (TIGIT) were elevated, but these levels significantly decreased with increased COVID-19 severity." (PMID 39928675, 2025).
breast carcinoma (13 papers, 2017 to 2026). "Clinically, OAS2 was associated with poor patient survival in breast cancer, supporting its potential as a stress-adaptive but pro-tumorigenic factor and reinforcing the adverse prognostic implications of COX-2." (PMID 41009689, 2025). "In contrast, the OAS2 gene showed mutations in only 1% of the total analyzed 986 breast cancer samples." (PMID 39633486, 2024). "In contrast, the OAS2 gene displayed mutations in a minimal 1% of the total samples, suggesting a relative rarity of genetic alterations in this gene within the breast cancer cohort." (PMID 39633486, 2024). "High mRNA expression of OAS1 and OAS3 was correlated with worse prognosis, while high mRNA expression of OAS2 was associated with better outcomes in all breast cancer patients." (PMID 32560641, 2020). "High mRNA expression of OAS1 and OAS3 were correlated with worse prognosis for all breast cancer patients, whereas OAS2 was associated with favorable prognosis." (PMID 32560641, 2020). "Six hub genes, including IFIT1, ISG15, IFI6, GOLM5, KLHL35, and OAS2, were associated with the total survival probability in breast cancer patients." (PMID 30646630, 2019). "In the ieu-a-1126 cohort, genes with causal relationships to breast cancer included GNB2, HADH, OAS2, OCIAD2, P4HA2, and PAFAH1B3." (PMID 41424847, 2026). "For example, EPST1 is considered to have immunomodulatory activity and show anti-tumor potential; OAS2, as a T cell exhaustion-related gene, has been shown to play a role in the regulation of immune responses in breast cancer and non-small cell lung cancer." (PMID 40259929, 2025). "The mutational spectrum of OAS1, OAS2, OAS3, and OASL genes in breast cancer patients from the TCGA dataset was investigated using the cBioportal database." (PMID 39633486, 2024). "OAS2 is related to many pathologies and diseases, including inflammation, autoimmune, malignant diseases, breast cancer, and colorectal cancer." (PMID 36162993, 2022). "It appears that the high mRNA expression of OAS2 represents more favorable outcomes in breast cancer patients." (PMID 36341357, 2022). "Further analysis of the correlation between the hub genes and the total survival time in breast cancer indicated that the high expression of GOLM5, KLHL35, and OAS2 was associated with a better survival probability." (PMID 30646630, 2019). "We constructed a model of doxycycline (Dox)-inducible expression of mutant or wild type Oas2 in T47D human breast cancer cells." (PMID 29117179, 2017). "Activation of OAS2 in the MMTV-PyMT model of breast cancer prevented pregnancy from increasing the number of lung metastases, a finding that establishes the OAS family as therapeutic targets for the development of agents designed to prevent pregnancy from driving breast cancer metastasis." (PMID 35505346, 2022). "High expression of OAS2 was found to be correlated with the prognosis of breast cancer." (PMID 36471952, 2022). "OAS1, OAS2, and OAS3 were significantly associated with prognosis for all breast cancer patients." (PMID 32560641, 2020). "Conversely, hub genes such as H2BC11, MX1, OAS2, and IFIT3 displayed greater expression in more aggressive breast cancer subtypes." (PMID 41009689, 2025). "To investigate the correlation between the expression levels of OAS1, OAS2, OAS3, and OASL genes and the survival outcomes in breast cancer patients, we utilized the Kaplan-Meier Plotter online bioinformatics tool." (PMID 39633486, 2024). "The OAS family genes (OAS1, OAS2, OAS3, and OASL) were found to be significantly upregulated in breast cancer cell lines and tissues compared to normal controls." (PMID 39633486, 2024). "The constructed predictive model showed that OAS1, OAS2, OAS3, and OASL genes can effectively predict the overall survival of breast cancer patients." (PMID 39633486, 2024).
breast carcinoma (continued). "A total of five drugs, Acetaminophen, Estradiol, Cyclosporine, Calcitriol, and Seocalcitol, demonstrated the capability to potentially reduce the expression levels of OAS1, OAS2, OAS3, and OASL, suggesting their prospective use in breast cancer treatment." (PMID 39633486, 2024). "The results revealed that breast cancer patients exhibiting increased expression of OAS1, OAS2, OAS3, and OASL genes had poor overall survival." (PMID 39633486, 2024). "Overall, these results highlight the critical roles of OAS1, OAS2, OAS3, and OASL in supporting the growth and proliferation of breast cancer cells, while also suggesting their involvement in modulating cellular migration." (PMID 39633486, 2024). "Results from UALCAN and GEPIA indicated that the mRNA levels of OAS1, OAS2, OAS3, and OASL were markedly higher (p-value < 0.05) in breast cancer samples compared to normal samples, aligning with the outcomes observed in cell lines." (PMID 39633486, 2024). "Next, we validated the promoter methylation levels of OAS1, OAS2, OAS3, and OASL genes in both breast cancer and control samples utilizing the OncoDB database." (PMID 39633486, 2024). "To further investigate the functional roles of the OAS family genes in breast cancer, we designed four siRNAs targeting OAS1, OAS2, OAS3, and OASL and transfected them into HOC1 cells." (PMID 39633486, 2024). "Our study observed significant correlations between the expression of OAS1, OAS2, OAS3, and OASL and various molecular and immune subtypes of breast cancer." (PMID 39633486, 2024). "In breast cancer, for instance, there is a notable upregulation of OAS genes such as OAS1, OAS2, OAS3, and OASL." (PMID 39633486, 2024). "The knockdown of OAS1, OAS2, OAS3, and OASL in HOC1 cells, validated by qRT-PCR and Western blot analyses, revealed their critical roles in breast cancer." (PMID 39633486, 2024). "Utilizing the TISIDB database, we explored the relationship between OAS1, OAS2, OAS3, and OASL expression in breast cancer across various immune and molecular subtypes." (PMID 39633486, 2024). "The results uncovered a significant correlation between the expression of OAS1, OAS2, OAS3, and OASL and all immune molecule subtypes in breast cancer." (PMID 39633486, 2024). "Treatment of other breast cancer cells SKBR3 and BT474 by compound KDM5-C70 also induced expression of OAS2, IFI44L, and IFI44, but to a lesser extent." (PMID 30080846, 2018). "The comprehensive examination of the mutational landscape of OAS1, OAS2, OAS3, and OASL genes in breast cancer patients revealed that OAS1, OAS3, and OASL exhibited an absence of mutations in all 986 analyzed breast cancer samples." (PMID 39633486, 2024). "Furthermore, the findings from GEPIA revealed that the expressions of OAS1, OAS2, OAS3, and OASL genes were notably more pronounced in the advanced stages of breast cancer compared to the early stages." (PMID 39633486, 2024). "High mRNA expression of OAS2 (HR = 0.26, 95%CI: 0.1–0.67, p = 0.0027), OAS3 (HR = 0.43, 95%CI: 0.26–0.7, p < 0.001), and OASL (HR = 0.47, 95%CI: 0.27–0.83, p = 0.0078) was correlated with better OS in basal-like breast cancer." (PMID 32560641, 2020). "The experimental data revealed significantly elevated mRNA levels of OAS1, OAS2, OAS3, and OASL in breast cancer cell lines relative to normal controls (p-value < 0.05)." (PMID 39633486, 2024). "Furthermore, our findings indicate a noteworthy negative correlation between OAS1, OAS2, OAS3, and OASL elevated gene expression and a substantial decrease in promoter methylation levels across breast cancer tissues." (PMID 39633486, 2024). "Additionally, results from HPA demonstrated a significant elevation in protein expression levels of OAS1, OAS2, OAS3, and OASL in breast cancer tissue samples as opposed to normal tissue samples." (PMID 39633486, 2024).
breast carcinoma (continued). "High mRNA expression of OAS2 (HR = 0.34, 95%CI: 0.17–0.67, p = 0.0011) was correlated with better OS in luminal A type cancers, whereas OASL was not related to prognosis in luminal A breast cancer." (PMID 32560641, 2020).
psoriasis (13 papers, 2016 to 2025). An autoimmune condition characterized by red, well-delineated plaques with silvery scales that are usually on the extensor surfaces and scalp. "In another study based on the expression profile analysis of psoriasis vulgaris diffuse genes, OASL/OAS2/OAS3 were considered as novel hub genes associated with psoriasis." (PMID 40560938, 2025). "Previous studies have identified the association between OAS2 and T lymphocyte activation in psoriasis and systemic lupus erythematosus, indicating its role as an active phase marker of these diseases." (PMID 38355637, 2024). "Decreased DNA methylation of OAS2 (2′-5′-Oligoadenylate Synthetase 2), encoding an antiviral protein, has been seen in psoriasis." (PMID 27572959, 2016). "OAS2 is a potential novel biomarker identified from proteomic profiles of psoriasis patients, who exhibited significantly higher OAS2 serum levels than healthy controls." (PMID 37546687, 2023). "Levels of keratinocyte-derived antiviral proteins (AVPs) of 2–5-oligoadenylate synthase 2 (OAS2) were found to be significantly elevated in both the epidermis and serum of psoriasis patients." (PMID 36172384, 2022). "OAS2 is a potential new sensitive biomarker, which can predict the activity and severity of psoriasis, and can evaluate the clinical treatment efficacy." (PMID 34926448, 2021). "As a new potentially sensitive biomarker, OAS2 is significantly up-regulated in psoriasis, a chronic inflammatory systemic disease, and can predict the severity and activity of the disease." (PMID 34880865, 2021). "Expression of OAS2 has been suggested as a biomarker for disease and it has been reportedly upregulated in psoriasis and squamous cell carcinoma patients and in mice in response to cigarette smoke and influenza virus." (PMID 28443095, 2017). "Despite differences in the specific residues targeted for methylation/demethylation, OAS2 expression was upregulated in all conditions and correlations between methylation and expression were seen in psoriasis and tongue SCC." (PMID 27572959, 2016). "We previously profiled DNA methylation in psoriatic epidermis using the Illumina 450K BeadChip platform and found hypomethylation of OAS2 in psoriasis compared to healthy controls." (PMID 27572959, 2016). "In summary, we used a high resolution quantitative method for analysis of OAS2 DNA methylation in psoriasis and SCCHN." (PMID 27572959, 2016). "Methylation status of 11 OAS2 CpG sites in psoriasis and control skin samples were successfully quantified using pyrosequencing." (PMID 27572959, 2016). "Therefore in this study, we performed pyrosequencing to detect DNA methylation of OAS2 in psoriasis, SCC of the mobile tongue and SCC of the tonsil." (PMID 27572959, 2016). "The general hypomethylation of OAS2 seen in psoriasis might functionally be related to OAS2 mRNA up-regulation, whereas in SCC of the mobile tongue, local decreased methylation at only two CpG sites (CpG2 and 3) seems sufficient to affect regulation of OAS2 expression." (PMID 27572959, 2016). "What's more, the use of biological agents suppressed the serum OAS2 and OAS3 at low levels and elevated the serum OAS1 level in patients with psoriasis." (PMID 38298734, 2024). "For example, OAS1, OAS2, OAS3, and IFI44L appear to be down-regulated by etanercept in responders to treatment for psoriasis." (PMID 30665420, 2019). "Overexpression of OAS2 was also seen in tonsillar SCC (P = 0.013, mean fold change = 2.4) but levels were much lower than in psoriasis and tongue SCC." (PMID 27572959, 2016). "In order to evaluate whether OAS2 DNA methylation could be involved in regulating gene expression, correlation between DNA methylation and gene expression was investigated using our previous gene expression profiling data for psoriasis (accession number GSE53431)." (PMID 27572959, 2016). "In addition, the use of biological agents suppressed the serum OAS2 and OAS3 and elevated the serum OAS1 level in psoriasis patients." (PMID 38298734, 2024).